CRP (C-reactive protein)
Diseases named in the same sentence as CRP in open-access papers (continued):
Sharing a sentence is not in itself a finding about the gene and the disease.
bacteremia (continued). "Therein, the area under the ROC curve in predicting bacteremia was 0.80 for procalcitonin and 0.79 for CRP." (PMID 32435627, 2020). "During early-stage infection, at a time when pneumococci have not recruited factor H yet on their surface to become complement-resistant, WT CRP is sufficient to decrease bacteremia." (PMID 33117400, 2020). "E-CRP-1 or E-CRP-2 would then bind to factor H on pneumococci, enabling complement activation by WT CRP/E-CRP-2-PCh complexes to proceed, resulting in the decrease in bacteremia." (PMID 33117400, 2020). "In both the complete study population and the younger age subgroup (<3 years) in our study, elevated CRP concentration was significantly higher in patients with bacteremia." (PMID 32429293, 2020). "We proposed a useful model for predicting bacteremia in febrile children, not only those with CRP but also other common laboratory parameters in the PED setting." (PMID 32429293, 2020). "Age, percentage of band and eosinophil, hemoglobin and CRP differed statistically between bacteremia and non-bacteremia encounters in the subgroup study." (PMID 32429293, 2020). "Children that were ill-appearing, admitted to the intensive care unit, or with significantly elevated CRP levels were more likely to have bacteremia secondary to CAP." (PMID 32582483, 2020). "Most likely, E-CRP-1 bound to a protein ligand present on the pneumococcal surface and, once bacteremia was already lower, endogenous mouse WT CRP bound to PCh to activate the complement system to reduce bacteremia further." (PMID 33117400, 2020). "Mortality, body temperature, heart and respiration rates, hematology, C-reactive protein, bacteremia, and serum protective antigen were monitored for 21 days post-exposure after the last of multiple doses." (PMID 33114429, 2020). "Human CRP has been shown to protect mice against infection with lethal doses of Streptococcus pneumoniae by decreasing bacteremia." (PMID 32903624, 2020). "Our findings confirm that complement activation by CRP-PCh complexes constitute the mechanism of CRP-mediated protection (decrease in bacteremia and increase in survival time) of mice against lethal pneumococcal infection." (PMID 32903624, 2020). "The NLR is more predictive of bacteremia than conventional infection markers (CRP, white blood cell count, and neutrophil count)." (PMID 32160890, 2020). "The synergy between various CRP species and clarithromycin in reducing bacteremia is just another example of cooperation between a molecule of the innate immune system and antibiotics." (PMID 33552084, 2020). "WT CRP (human or murine or both) would bind to PCh on pneumococci, activate the complement system, and reduce bacteremia." (PMID 33117400, 2020). "According to the multivariate logistic regression analysis, higher MIC of rifampin, increased SAPS II, and elevated CRP/albumin ratio on the day of bacteremia were significantly related to mortality." (PMID 32408478, 2020). "The present study found that age ≤90 days, higher CRP and DNI levels, and the presence of VUR were significantly associated with bacteremia in infants with febrile UTI." (PMID 32161316, 2020). "More broadly, it has been identified as a good predictor of bacteremia in emergency departments, and reported as better than CRP or leukocyte count." (PMID 30658580, 2019). "In murine models of pneumococcal infection, passively administered human CRP has been shown to be protective against lethal pneumococcal infection, that is, CRP decreases bacteremia and enhances survival of infected mice." (PMID 30863393, 2019). "The NLR has been found to be more accurate than CRP in the prediction of bacteremia or the severity of community-acquired pneumonia." (PMID 31781524, 2019). "Examination of tissue and blood from animals that succumbed to disease revealed elevated serum C-reactive protein, positive terminal bacteremia, gross necropsy lesions, and histologic lesions consistent with fulminant anthrax infection." (PMID 30774997, 2019).
bacteremia (continued). "The high levels of ESR and CRP were found in patients with endogenous endophthalmitis, an ocular inflammation that occurs concurrently with bacteremia." (PMID 30411142, 2019). "Area under receiving operating curve of C-reactive protein, lactate and procalcitonin for predicting bacteremia and 28-day mortality were also evaluated." (PMID 31212806, 2019). "This retrospective study was implemented to evaluate performances of PCT and CRP to detect bacteremia in 614 febrile episodes from patients with hematological malignancy." (PMID 31821331, 2019). "C-reactive protein (CRP) and procalcitonin are the most studied inflammatory markers of bacterial sepsis, particularly for making decisions regarding antibiotic treatment in the ICU." (PMID 31648506, 2019). "Serum procalcitonin (PCT) has been described as a better biomarker for bacterial sepsis than CRP, while other found serum CRP as better predictor for lobar consolidation and pleural effusion than PCT." (PMID 30940126, 2019). "Procalcitonin and CRP are the most used biomarkers to discriminate bacterial sepsis from other inflammatory diseases." (PMID 31648506, 2019). "Lower blood pressure, platelet count, and HCO3− level, higher CRP and creatinine level, and the presence of bacteremia were more commonly observed in the case group than in the control group." (PMID 30405714, 2018). "They showed that the NLR together with lymphocytopenia are better predictors for bacteremia than CRP." (PMID 30234089, 2018). "One study showed that for patients in the emergency unit NLR can be used as a simple, and even better, infection marker for predicting bacteremia than leucocytes and CRP." (PMID 30234089, 2018). "The activation of classical complement pathways, such as the C3 complement component, is driven by CRP, resulting in opsonisation of pneumococcus and in limiting rapid bacteremia during pneumococcal infection." (PMID 30333823, 2018). "In the study performed by our research group some years ago we detected cut-off level of 99.5 mg/L for CRP to identify patients with bacteremia (sensitivity of 80.6% and specificity of 82.1%)." (PMID 30344287, 2018). "Laboratory tests suggested that the proportions of white blood cells, neutrophils, and C-reactive protein were increased, and the blood culture suggested Salmonella bacteremia." (PMID 29947649, 2018). "According to our results, neutrophil CD64 expression is a good diagnostic tool for the diagnosis of bacteremia in febrile neutropenia patients, and CD64 is superior to CRP and ESR." (PMID 27348760, 2017). "Our results are consistent with those studies, and the combination of high CRP and low albumin levels appears to readily predict the prognosis of S. maltophilia bacteremia." (PMID 28938875, 2017). "Biomarkers such as PCT (procalcitonin), CRP (C-reactive protein) and sTREM (soluble triggering receptor expressed on myeloid cells) are shown to be sensitive predictors of bacteremia (Bloodstream infection)." (PMID 28235076, 2017). "The most widely studied biomarkers in patients with suspected bacterial sepsis are C-reactive protein (CRP) and procalcitonin (PCT)." (PMID 28727802, 2017). "Thus, the hypothesis that nonsurgical periodontal therapy might reduce the bacterial load and associated bacteremia, therefore reducing the inflammatory stress during pregnancy and IL-6 cascade, contributes to reduction in CRP levels and, consequently, the incidence of APO." (PMID 29017560, 2017). "At 28 d, most CBC parameters and C-reactive protein returned to pre-irradiation levels; however, bacteremia was observed in the peripheral circulation." (PMID 28852188, 2017). "An important study on bacteremia caused by antibiotic-resistant pathogens (ARP) in CAP reported that the risk factors for ARP bacteremia in CAP patients were; previous antibiotic use and C-reactive protein < 22.2 mg/dL." (PMID 27999274, 2016).
bacteremia (continued). "It was shown that the NLR values differentiate bacteremia significantly better in patients admitted to the emergency department than the routine parameters of the CRP level, WBC count and neutrophil count." (PMID 27068888, 2016). "We used multivariate logistic regression analysis adjusted with PA, CRP, abdominal tenderness, and mechanical ileus as covariates to validate the independent risk factors related to post-SEMS insertion fever, SIRS and bacteremia." (PMID 25918522, 2015). "C-reactive protein was significant higher among the patients with biliary tract infection and primary bacteremia than the patients with acute gastroenteritis." (PMID 25602257, 2015). "In multivariate analysis, the CRP level was only risk factor related to colon SEMS insertion-related SIRS, except for fever and bacteremia." (PMID 25918522, 2015). "In the three bitches with positive blood cultures (bacteremia), the concentrations of CRP were 97, 272 and 298 mg/L, concentrations of SAA were 56.6, 114.7 and 117.9 mg/L and concentrations of albumin 21, 26 and 20 g/L." (PMID 25430894, 2014). "A Lab-score ≥3 was not able to detect a suspected methicillin-sensitive Staphylococcus aureus occult bacteremia in a 34 days old infant presenting with fever for 15 hours, CRP 27 mg/L, PCT 0.19 ng/mL, WBC count 28’600/mm3 and band count 860/mm3." (PMID 25503770, 2014). "Although laboratory inflammation markers such as peripheral white blood count and C-reactive protein were predictors of bacteremia in previous research, they were useless in our study for both age groups." (PMID 24298435, 2013). "In summary, the IPS and widely used infection parameters, including CRP or WBC, yielded a poor diagnostic performance for the detection of infection or bacteremia." (PMID 24349403, 2013). "The IPS and widely used biomarkers, including CRP and WBC, showed a low diagnostic performance regarding the identification of infection and bacteremia." (PMID 24349403, 2013). "Recently, we showed that the NLCR proved to be a simple infection marker with discriminatory capacity in predicting bacteremia in infectious emergency admissions as compared to CRP level, neutrophil count and WBC count." (PMID 23049706, 2012). "In order to establish bacteremia and monitor the development and recovery of bacteremia, bacterial burden, white blood cell count, C-reactive protein and procalcitonin levels in blood were measured at each time point." (PMID 23226457, 2012). "Regrettably, the sample size of this study was small; larger studies are thus needed to further evaluate the value of sTREM-1, PCT, and CRP levels in the diagnosis of bacteremia." (PMID 22809118, 2012). "PCT appeared to be a more relevant marker than CRP for diagnosing bacterial sepsis at earlier stages, with the mean sensitivity of 77.93%, specificity of 81.84%, and a cut-off of 8.92 ng/mL." (PMID 23198119, 2011). "In an emergency care setting, both lymphocytopenia and NLCR are better predictors of bacteremia than routine parameters like CRP level, WBC count and neutrophil count." (PMID 21034463, 2010). "Subsequently, the bacteremia as well as cytokines from the periodontal lesion will stimulate the hepatocytes and leucocytes to produce CRP and IL-6." (PMID 20407653, 2009). "A prospective study was performed to assess the potential value of IL-6, IL-8 and C-reactive protein serum levels to predict severe bacterial infection or bacteremia in febrile neutropenic children with cancer during chemotherapy." (PMID 18321393, 2008). "Accumulating evidence suggest that peri-implant inflammation can contribute to a sustained systemic low-grade inflammatory state characterized by elevated inflammatory mediators, like interleukin (IL)-6 and C reactive protein, episodic bacteremia, and metabolic alterations." (PMID 41867638, 2026).
bacteremia (continued). "Bacteremia (odds ratio (OR): 32.232, 95%CI: [2.558-406.068], P = 0.007), CRP > 162.375 mg/L (OR: 7.499, 95% CI: [2.044–27.513], P = 0.002), and delayed operation > 9.50 days (OR: 7.462, 95% CI: [1.828–30.459], P = 0.005),were high-risk factors for the occurrence of disseminated infection." (PMID 40437616, 2025). "Logistic regression identified bacteremia (OR: 32.232, 95% CI: [2.558-406.068], P = 0.007), CRP > 162.375 mg/L (OR: 7.499, 95% CI: [2.044–27.513], P = 0.002), and surgical delay > 9.50 days (OR: 7.462, 95% CI: [1.828–30.459], P = 0.005) as independent risk factors." (PMID 40437616, 2025). "Also, IL-6, PCT and CRP combination demonstrated 90% sensitivity and 85% specificity for predicting mortality with bacteremia." (PMID 41011807, 2025). "CRP elevation may also reflect bloodstream infections and bacterial sepsis, which are common in advanced HIV." (PMID 40581751, 2025). "CRP and procalcitonin levels were elevated, mimicking bacterial sepsis." (PMID 40864107, 2025). "Furthermore, when the presence of bacteremia was included as an additional criterion, the IL-6 and CRP combination reached a sensitivity of 84%; however, the specificity remained considerably low at 34%." (PMID 41011807, 2025). "While SAA achieved 100% sensitivity for bacteremia (vs. CRP’s 68%), neither marker reliably predicted individual risk." (PMID 40647525, 2025). "We propose that, in circulation, CRP cooperates with SAP to reduce bacteremia." (PMID 40740789, 2025). "In this retrospective study of neonates diagnosed with TTN, we found that CRP levels measured 12-24 hours after birth were significantly associated with neonatal bacteremia, whereas CRP levels measured immediately after admission were not." (PMID 40809608, 2025). "However, the bacteremia in mice treated with both WT CRP and E-CRP-1 (group F) was found to be significantly lower than bacteremia in untreated mice (group A) at time points 36 h and 44 h." (PMID 40740789, 2025). "Consistent with the survival curves of mice treated with E-CRP-1 alone 30 min prior to inoculation, these mice had significantly lower bacteremia than in untreated mice and at the same time, significantly higher than mice treated with WT CRP alone 30 min prior to inoculation." (PMID 40740789, 2025). "Notably, while white blood cell counts were ineffective in detecting bacteremia, low platelet counts and elevated C-reactive protein (CRP) levels were helpful indicators." (PMID 39677171, 2024). "Additionally, definitive carbapenem treatment was more likely to be administered to patients with a higher Pitt bacteremia score (2.7 ± 2.9 versus 1.6 ± 2.1, p = 0.02) and a higher CRP level (20.6 ± 11.2 versus 16.6 ± 8.7, p = 0.04)." (PMID 39200009, 2024). "Episode #1: A 61-year-old male with a history of liver fibrosis with multiple biliary dilations (Caroli-like disease) presented daily fever and the progressive elevation of acute phase reactants (CRP > 15 mg/dL) with continuous bacteremia due to E. casseliflavus (isolate ECAS-1219a)." (PMID 39770714, 2024). "A meta-analysis evaluated serum procalcitonin, CRP and interleukin-6 as predictors of bacteremia." (PMID 39694764, 2024). "In another study, UVA revealed AlkPh, GGT, and cholinesterase (but not bilirubin, transaminases, and CRP) as significantly associated with bacteremia." (PMID 39202194, 2024). "A higher level of CRP (OR = 1.010, 95% CI = 1.007 to 1.013; p ≤ 0.05) and the utilization of CVVH treatment (OR = 2.93, 95% CI = 1.13 to 7.59; p ≤ 0.05) were found to be associated with an elevated risk of bacteremia." (PMID 37768395, 2023). "Although CRP is widely used to indicate bacterial sepsis in neonates and children, it may have several disadvantages, like a late response." (PMID 37684308, 2023). "This increase in CRP may be due to either a progression of systemic inflammation due to aggravated liver failure or bacterial sepsis or it may be a marker of liver recovery." (PMID 36983259, 2023).
bacteremia (continued). "In addition, treatment with human CRP prior to pneumococcal challenge has been shown to protect mice from severe pneumococcal bacteremia, and while the exact mechanisms behind the protection are not known, it is thought to be related to complement activation." (PMID 36622851, 2023). "Furthermore, multivariable logistic regression analysis revealed that higher CRP level (OR = 1.01) and CVVH treatment (OR = 2.93) were associated with an increased risk of bacteremia." (PMID 37768395, 2023). "coli infection, C-reactive-protein levels over 80 mg/L, and bacteremia." (PMID 37587378, 2023). "Previous studies have also reported that CRP levels may be an indicator of bacteremia in young infants and children." (PMID 37679686, 2023). "Moreover, in patients with bacteremia, CRP levels were higher, Hb concentrations were lower, and Z scores of Hb were also lower compared to the non-bacteremia group." (PMID 37628401, 2023). "A higher BT at triage, increased total neutrophil count, and elevated CRP levels may be useful for identifying bacteremia in young febrile infants admitted to the PED." (PMID 37679686, 2023). "Whereas, CRP proved useless in predicting bacteremia, which was similar to our study." (PMID 35804024, 2022). "In neonates, CRP levels were shown to be significantly higher in the fungal sepsis group than in bacterial sepsis group, while in adult patients, they were shown not to be significantly different between the candidemia and bacteremia groups." (PMID 35740137, 2022). "Additionally, in another study, PCT was more sensitive and specific than CRP in patients with bacterial sepsis." (PMID 36010153, 2022). "Apart from transient bacteremia detected by blood culture, we also examined laboratory parameters, especially the CRP values of our participants, as markers for the chronic inflammation that constitutes one of the main factors for cardiovascular risk and subsequently for mortality." (PMID 34297188, 2022). "In agreement with previous recent studies, the changes in bacteremia patient serum hepcidin correlated well with the changes in CRP, except in the case of the fewer in number infections with Gram-positive bacteria, in which CRP was not significantly reduced after treatment." (PMID 35741214, 2022). "The early increase (<6 h) in NLR following acute physiological stress could confer on NLR the role of marker of acute stress earlier than other laboratory parameters (e.g., white blood cell count, bacteremia, C-reactive protein, CRP)." (PMID 35408994, 2022). "Previous studies reported that high respiratory and/or pulse rate, elevated C-reactive protein and/or lactate dehydrogenase level, need for mechanical ventilation, hypoxia, combined bacteremia, and preexisting chronic lung disease were more common in mortality cases among adult patients with PCP." (PMID 36291531, 2022). "Patients must have high inflammation markers [erythrocyte sedimentation rate (ESR), C-reactive protein (CRP) or procalcitonin (PCT), among others), any other causes of infectious and inflammatory origin, including bacterial sepsis, staphylococcal or streptococcal shock syndromes must be ruled out." (PMID 35442269, 2022). "Biomarkers such as procalcitonin (PCT) and CRP are helpful in bacterial sepsis, and CRP, ferritin, and IL-6 may be more useful in viral sepsis." (PMID 34692364, 2021). "In our univariate analyses, we found risk factors of mortality from LM bacteremia were the following: respiratory syndromes, shock, neoplasm, elevated liver enzymes, LDH, and CRP; higher scores of MED, MEWS, NEWS, and qSOFA; and the usage of vasopressors, particularly patients with neoplasm." (PMID 34827066, 2021). "The present study is the first to demonstrate that although the half-life of Fh15 in circulation is short, it is able to significantly suppress bacteremia, endotoxemia, CRP, and PCT during the early phase of an E. coli-induced acute sepsis (8 hours) in a rhesus macaque model." (PMID 34937173, 2021).